ADAMTSL4 (ADAMTS like 4)
Description:
Positive regulation of apoptosis. May facilitate FBN1 microfibril biogenesis.
Synonyms: ADAMTSL-4; TSRC1; DKFZP434K1772; ECTOL2
Tractability: Antibody: UniProt places it where antibodies can reach, with high confidence; UniProt predicts a signal peptide or a membrane-spanning region; its Gene Ontology location is reachable by antibodies, with medium confidence; the Human Protein Atlas places it where antibodies can reach.
Gene: Protein-coding gene on chromosome 1 (150,549,369 to 150,560,937, forward strand). Ensembl gene ENSG00000143382.
Subcellular location: Secreted, extracellular space, extracellular matrix
Subcellular location (Human Protein Atlas): Cytosol; Plasma membrane; Predicted to be secreted
Pathways (Reactome):
Disease: Defective B3GALTL causes PpS
Metabolism of proteins: O-glycosylation of TSR domain-containing proteins
Gene Ontology:
Molecular function: protease binding; protein binding
Biological process: positive regulation of apoptotic process; extracellular matrix organization
Cellular component: extracellular matrix; elastic fiber; endoplasmic reticulum lumen; interstitial matrix
Genetic constraint (gnomAD): Loss-of-function variants: 97 observed, 124.75 expected, observed/expected ratio (o/e) 0.78, 90% interval 0.66 to 0.92. The upper end of that interval is the gene's LOEUF score, 0.92, which puts it in group 3 of 6, group 1 being the genes least tolerant of losing a copy. Missense variants: 1,408 observed, 1,507.5 expected, observed/expected ratio (o/e) 0.93, 90% interval 0.89 to 0.98. Synonymous variants: 592 observed, 595.55 expected, observed/expected ratio (o/e) 0.99, 90% interval 0.93 to 1.06.
Homologues: Orthologues: chimpanzee ADAMTSL4 (99% identical), macaque ADAMTSL4 (97% identical), pig ADAMTSL4 (85% identical), dog ADAMTSL4 (83% identical), rabbit ADAMTSL4 (80% identical), guinea pig ADAMTSL4 (76% identical), mouse Adamtsl4 (76% identical), rat Adamtsl4 (76% identical), tropical clawed frog adamtsl4 (45% identical). Paralogues in human: THSD4 (37% identical), PAPLN (23% identical), ADAMTS7 (23% identical), ADAMTS9 (22% identical), ADAMTS12 (22% identical), ADAMTS16 (21% identical), ADAMTS18 (21% identical), ADAMTSL2 (21% identical), ADAMTS20 (20% identical), ADAMTSL1 (20% identical), ADAMTS13 (19% identical), ADAMTSL3 (19% identical), and 13 more.
Diseases named in the same sentence as ADAMTSL4 in open-access papers:
ADAMTSL4 is named in the same sentence as 46 diseases in open-access papers, as found by Europe PMC text mining. Sharing a sentence is not in itself a finding about the gene and the disease. The quoted sentences say what the papers report.
ectopia lentis (18 papers, 2012 to 2025). "Pathogenic variants in ADAMTSL4 are an important cause of isolated ectopia lentis with an increasing number of genetically confirmed cases internationally." (PMID 41243720, 2025). "ADAMTSL4-related disease tends to present at a younger age and be associated with higher myopia than other forms of ectopia lentis (such as FBN1)." (PMID 41243720, 2025). "Mutations in ADAMTS10 and ADAMTS17 phenocopy mutations in ADAMTSL4 (ectopia lentis) and ADAMTSL2 (acromelic dysplasias), suggesting common functional pathways, and ADAMTSL3 also binds directly to ADAMTS10." (PMID 38324186, 2024). "Herein, we report the case of a six-year-old girl with a confirmed diagnosis of isolated ectopia lentis caused by a compound heterozygous ADAMTSL4 gene mutation." (PMID 38146062, 2023). "Genetic variants were identified in four genes: FBN1 (associated with Marfan syndrome and cardiovascular complications; n = 6), ADAMTSL4 (associated with non-syndromic ectopia lentis; n = 2), LTBP2 (n = 1) and ASPH (n = 1)." (PMID 37107549, 2023). "Here, we report on two new cases of craniosynostosis with ectopia lentis, each harboring recessive mutations in ADAMTSL4." (PMID 35378950, 2022). "In humans, recessive isolated ectopia lentis (subluxation or dislocation of the human crystalline lens) and ectopia lentis et pupillae are caused by ADAMTSL4 loss‐of‐functions variants (OMIM610113)." (PMID 35233794, 2022). "Curiously, several instances of a seemingly novel syndrome involving only craniosynostosis and ectopia lentis have recently been reported to be caused by recessive mutations in ADAMTSL4, a poorly characterized gene as of yet." (PMID 35378950, 2022). "Mutations in ADAMTS17 cause WMS-like syndrome with ectopia lentis and ADAMTSL4 mutations cause isolated ectopia lentis and ectopia lentis et pupillae." (PMID 30060141, 2018). "All the genes associated with ectopia lentis phenotypes to date, (ADAMTSL4, FBN1, LTBP2, ADAMTS10, ADAMTS17) included in the clinical exome employed, revealed several genetic variants in these genes." (PMID 29751740, 2018). "In humans, mutations in ADAMTSL4 are clearly causative for ectopia lentis (EL) and congenital abnormalities of the iris." (PMID 29121641, 2017). "ADAMTSL4, mutated in isolated ectopia lentis and ectopia lentis et pupillae, enhances fibrillin-1 assembly in cultured cells." (PMID 28176809, 2017). "ADAMTSL4 mutations cause isolated ectopia lentis (dislocation of the ocular lens) due to impaired fibrillin-1 rich suspensory ligament of the lens." (PMID 27857980, 2016). "Mutations in ADAMTS17 cause a Weill-Marchesani-like syndrome, and mutations in ADAMTSL4 cause autosomal recessive isolated ectopia lentis." (PMID 22242013, 2012). "Mutations in ADAMTSL4 have been reported to cause ectopia lentis and ectopia lentis et pupillae." (PMID 37057399, 2023). "Besides focal retinal pigment epithelium defects, homozygous disruption of murine Adamtsl4 resulted in a defect in the anchoring of zonule fibers to the lens surface, causing ectopia lentis, confirming its role in zonule formation." (PMID 35233794, 2022). "ADAMTSL4 mutation was reported to participate in the formation of ectopia lentis." (PMID 30728876, 2019). "ADAMTSL4 acts as a FBN1 binding protein that mediates microfibril assembly in the zonule fibers of the human eye leading to isolated ectopia lentis (IEL) if mutated." (PMID 23874219, 2013). "Biallelic ADAMTSL4 mutations cause ectopia lentis et pupillae (MIM 225200) and isolated ectopia lentis (MIM 225100)." (PMID 38324186, 2024). "As a screening factor for autosomal-recessive isolated ectopia lentis, ADAMTSL4 has been mainly reported to participate in the microfibril formation and function." (PMID 30728876, 2019). "Taking into account that the ADAMTSL4 gene is considered responsible for most cases of isolated ectopia lentis in the European population, we started the present study by sequencing all 20 exons and exon-intron boundaries of this gene." (PMID 29751740, 2018).
ectopia lentis (continued). "Patients with isolated ectopia lentis (FBN1 or ADAMTSL4 gene mutation) do not have skeletal involvement." (PMID 39421111, 2024).
glioblastoma (6 papers, 2019 to 2024). The most malignant astrocytic tumor (WHO grade IV). "More recently ADAMTSL4 expression was identified in glioma stem-like cells contributing to a five gene signature associated with bad prognosis of patients with primary glioblastoma, suggesting that ADAMTSL4 might have contrasting roles depending on cell origin." (PMID 33805340, 2021). "Among genes whose high expression correlates with decreased survival in glioblastoma, we identified several components of the “matrisome” and associated factors (FAM20C, SEMA3F, ADAMTSL4, ADAMTS14, SERPINA5, and CRELD1)." (PMID 32488114, 2020). "And we found that ADAMTSL4 as a secreted glycoprotein may become a novel immune-related biomarker for primary glioblastoma multiforme (GBM)." (PMID 38701413, 2024). "In glioblastoma multiforme (GBM, WHO grade IV), ADAMTSL4 has been reported to make a contribution to predicting survival." (PMID 36761753, 2023).
glioma (5 papers, 2019 to 2026). A benign or malignant brain and spinal cord tumor that arises from glial cells (astrocytes, oligodendrocytes, ependymal cells). "In the ‘Distribution’ section, users can display one gene distribution pattern for each glioma subtype by selecting a dataset (e.g., ‘mRNAseq_325’) and inputting a gene name of interest (e.g., ADAMTSL4)." (PMID 33662628, 2021). "Due to the prominent heterogeneity across different glioma grades, the ADAMTSL4 expression from both CGGA and TCGA database was analyzed according to the WHO grade." (PMID 30728876, 2019). "In this study, we first tested the expression of ADAMTSL4 between normal brain tissue, lower-grade gliomas (LGG), and GBM (WHO grade IV)." (PMID 30728876, 2019). "Recently, we revealed that ADAMTSL4 was highly expressed in the glioma stem-like cells and made a great contribution in the signature predicting the survival of GBM (WHO grade IV)." (PMID 30728876, 2019). "Recently, we revealed that ADAMTSL4 was upregulated in the glioma stem-like cell lines compared with conventional glioma cell lines." (PMID 30728876, 2019). "In this study, we demonstrated that glioma CEBPD directly binds to and activates the promoter regions of miR-4257 and miR-3156, located within the genes ADAMTSL4 and ANKRD30BP3, respectively." (PMID 41736026, 2026). "In the CGGA RNA-seq database, ADAMTSL4 was significantly higher expressed in GBM (WHO grade IV) compared to lower-grade gliomas (LGG, including grade II and grade III gliomas) (p < 0.001)." (PMID 30728876, 2019). "We found that ADAMTSL4 expressed significantly higher in GBM (WHO grade IV), compared to normal brain tissue (p<0.05), indicating ADAMTSL4 plays an important role in glioma oncogenesis." (PMID 30728876, 2019). "This was also validated in the TCGA cohort (p < 0.0001), which indicated that higher ADAMTSL4 expression was enriched in GBM and may play a critical role in the malignant progression of glioma." (PMID 30728876, 2019).
Marfan syndrome (3 papers, 2022 to 2024). A disorder of the connective tissue. "Mutations in the ADAMTSL4 gene (1q21.2), inherited in a recessive manner, and dominant mutations in the FBN1 gene (15q21.1), the same gene that causes Marfan syndrome, have been identified as causes of isolated EL." (PMID 39202561, 2024). "The lens tends to dislocate upward in the eyes of patients with Marfan syndrome, while interior-nasal and interior-temporal dislocations are commonly seen in homocystinuria and ADAMTSL4-related EL, respectively." (PMID 36303223, 2022).
nasopharyngeal carcinoma (2 papers, 2017 to 2022). A carcinoma arising from the nasopharyngeal epithelium. "Deregulation of ADAMTSL4 has also been reported in nasopharyngeal carcinoma, acute lymphoblastic leukaemia and oesophageal squamous cell carcinoma." (PMID 36354023, 2022). "In our previous study, five different secretory proteins, including GSN, ADAMTSL4, CALR, PPIA and TXN, have been identified to be associated with the nasopharyngeal carcinoma (NPC) metastasis." (PMID 28107202, 2017).
amblyopia (1 paper, 2023). Decreased vision that results from abnormal visual development. "Mutations in the ADAMTSL4 gene can result in ocular abnormalities, including dislocation of the lens, congenital abnormalities of the iris, refractive errors that may lead to amblyopia, early-onset cataract, increased intraocular pressure, and retinal detachment." (PMID 38146062, 2023).
autism spectrum disorder (1 paper, 2023). A spectrum of developmental disorders that includes autism, and Asperger syndrome. "GIGYF1, which is associated with Autism Spectrum Disorder (ASD) and indirectly linked to AD, as well as ADAMTSL4, involved in the metabolism of amyloidogenic peptides in AD, were both down-regulated in ACD patients." (PMID 38040763, 2023).
Burkitt lymphoma (1 paper, 2022). A rare form of malignant mature B-cell non-Hodgkin lymphoma. "Analysing gene expression data of Burkitt lymphoma transcriptome sequencing from African patients revealed six biomarkers (ADAMTSL4, SEMA5B, ADAMTS15, THBS2, SPON1 and THBS1) as possible indicators for diagnostic and prognostic targets towards BL management." (PMID 36354023, 2022).
Cirrhosis (1 paper, 2024). A chronic disorder of the liver in which liver tissue becomes scarred and is partially replaced by regenerative nodules and fibrotic tissue resulting in loss of liver function. "ADAMTSL4 is a secreted glycoprotein that contributes to ECM homeostasis, and was previously demonstrated to induce fibrillin-1 deposition in cirrhosis." (PMID 38603681, 2024).
congenital glaucoma (1 paper, 2024). "Although we cannot completely dismiss the possibility that congenital glaucoma may be solely attributed to biallelic recessive ADAMTSL4 variants, we find it improbable." (PMID 38891949, 2024).
coronary artery disease (1 paper, 2024). "Interestingly, in a recent observational study, ADAMTSL4 variants were associated with protection from coronary artery disease in two cohorts of high-risk patients, and pathogenic variants in ADAMTSL4 were reported in spontaneous coronary artery dissection." (PMID 38324186, 2024).
COVID-19 (1 paper, 2021). A disease caused by infection with severe acute respiratory syndrome coronavirus 2. "Consistent with the transcription analysis, several proteins (e.g., LDHA, ADAMTSL4) related to positive regulation of apoptotic processes were preferentially present in critical COVID-19 patients." (PMID 34315889, 2021).
emphysema (1 paper, 2018). "Our data suggest that ADAMTSL-4 may be involved in emphysema pathogenesis, however its role remain to be further elucidated." (PMID 29476075, 2018). "We found significantly increased ADAMTSL-4 expression in ATII cells and lung tissue in emphysema in comparison with non-smokers." (PMID 29476075, 2018).
glaucoma (1 paper, 2024). Increased pressure in the eyeball due to obstruction of the outflow of aqueous humor. "ADAMTSL4 protein expression was observed in the anterior segment of both the adult human and zebrafish larvae’s eye, including tissues associated with glaucoma." (PMID 38891949, 2024). "In this study, we selected another enriched gene, ADAMTSL4, to examine the presence of its encoded protein in glaucoma-related ocular tissues using confocal FIHC." (PMID 38891949, 2024). "The intracellular accumulation, along with increased PDI expression in HEK-293T cells of two of the identified ADAMTSL4 variants (p.Arg774Trp and p.Arg98Trp), indicated the induction of ER stress, which is associated with various pathological conditions, including glaucoma." (PMID 38891949, 2024). "The detection of the ADAMTSL4 protein in the ocular anterior segment of both adult human and zebrafish larvae suggests that it has evolutionary conserved and specific roles in the physiology of these ocular tissues, as well as in glaucoma." (PMID 38891949, 2024). "The four enriched genes are expressed in ocular tissues and the presence of ADAMTSL4 and CPAMD8 proteins has been demonstrated in anterior segment structures of the eye involved in glaucoma." (PMID 38891949, 2024).
heart failure (1 paper, 2024). Inability of the heart to pump blood at an adequate rate to meet tissue metabolic requirements. "During experimental heart failure in mice, cardiac ADAMTSL4 levels increase, indicating a role in the failing heart." (PMID 38324186, 2024).
lymph node metastasis (1 paper, 2017). "The ELISA analysis demonstrated that the serum ADAMTSL4 level was highly associated with the NPC lymph node metastasis and the clinical stage." (PMID 28107202, 2017). "The results revealed that serum ADAMTSL4 expression level was closely correlated with lymph node metastasis and clinical stage (P<0.05) in NPC patients, and it was able to discriminate metastasis NPC from non-metastasis NPC with a sensitivity of 75.6% and a specificity of 64.7%." (PMID 28107202, 2017). "Furthermore, the result of immunohistochemistry analysis indicated that the expression level of ADAMTSL4 was highly correlated with the NPC lymph node metastasis, the distant metastasis and the clinical staging." (PMID 28107202, 2017).
migraine (1 paper, 2023). "Interestingly, in addition to migraine, ADAMTSL4 has recently been identified as a risk gene for migraine and cervical artery dissection." (PMID 36808568, 2023). "Among the overlapping genes, four (ADAMTSL4, EHMT2, SUGP1, and MAU2) were associated with migraine, headache, and at least five glycemic traits." (PMID 36808568, 2023).
Obesity (1 paper, 2025). Accumulation of substantial excess body fat. "This analysis identified proteins not previously associated with childhood obesity, to the best of our knowledge, including A2M, PON3, ADAMTSL4, HSPG2 and MAGEB6B, all of which showed decreased levels in children with obesity." (PMID 39972214, 2025).
ovarian carcinoma (1 paper, 2017). A malignant neoplasm originating from the surface ovarian epithelium. "In addition, Jianping Liu and his colleagues found that the overexpression of ADAMTSL4 could facilitate the tumor necrosis factor (TNF) induced OV-90 cells (ovarian cancer cells) apoptosis." (PMID 28107202, 2017).
Peters plus syndrome (1 paper, 2020). "Two of the overlapping genes ADAMTS17 and ADAMTSL4 participate in the pathway: Defective B3GALTL causes Peters-plus syndrome (PpS)." (PMID 32925905, 2020).
Primary glaucoma (1 paper, 2015). "Finally, mutations in closely related genes, ADAMTS10 and ADAMTSL4, are known to be involved in primary glaucoma and other ocular connective tissue disorders in both man and dog." (PMID 26474315, 2015).
spontaneous coronary artery dissection (1 paper, 2020). The spontaneous occurrence of a dissection of the coronary artery. "Spontaneous coronary artery dissection (SCAD) is a cause of myocardial infarction Here, the authors present a genome-wide association study of SCAD, finding an association at 1q21.2 which potentially affects expression of ADAMTSL4." (PMID 32887874, 2020).
thyroid cancer (1 paper, 2023). "In a real-world experiment, the RT-qPCR results were consistent with the bioinformatic analysis, confirming that ADAMTSL4, DOCK6, FAM111B, and SEMA6B were expressed at higher levels in thyroid cancer cells (p < 0.05), while MRPS10 and PSMB7 were expressed at lower levels (p < 0.05)." (PMID 36761753, 2023).